TPTE2P2 (TPTE2 pseudogene 2)
Gene: Transcribed unprocessed pseudogene on chromosome 13 (52,219,528 to 52,297,828, reverse strand). Ensembl gene ENSG00000272281.
Diseases named in the same sentence as TPTE2P2 in open-access papers:
TPTE2P2 is named in the same sentence as 2 diseases in open-access papers, as found by Europe PMC text mining. Sharing a sentence is not in itself a finding about the gene and the disease. The quoted sentences say what the papers report.
gastric cancer (1 paper, 2019). A primary or metastatic malignant neoplasm involving the stomach. "Another publication also reported TPTE2P2 as one of the key genes identified in gastric cancers, implying its crucial role in certain cancers." (PMID 31921812, 2019).
TPTE2P2 also shares sentences with these, for which no sentence is quoted: cancer (1 paper).